PTPRD (protein tyrosine phosphatase receptor type D)
Description:
Can bidirectionally induce pre- and post-synaptic differentiation of neurons by mediating interaction with IL1RAP and IL1RAPL1 trans-synaptically. Involved in pre-synaptic differentiation through interaction with SLITRK2.
Synonyms: R-PTP-delta; PTPD; HPTP; HPTPD; HPTPDELTA; RPTPDELTA
Tractability: Antibody: its Gene Ontology location is reachable by antibodies, with high confidence; UniProt predicts a signal peptide or a membrane-spanning region. PROTAC: ubiquitination databases record sites on it; its protein half-life has been measured.
Target class: Enzyme; Hydrolase
Gene: Protein-coding gene on chromosome 9 (8,314,246 to 10,613,002, reverse strand). Ensembl gene ENSG00000153707.
Subcellular location: Membrane
Subcellular location (Human Protein Atlas): Vesicles; Nucleoplasm
Pathways (Reactome):
Neuronal System: Receptor-type tyrosine-protein phosphatases; Synaptic adhesion-like molecules
Gene Ontology:
Molecular function: protein binding; cell adhesion molecule binding; protein tyrosine phosphatase activity; signaling receptor binding; transmembrane receptor protein tyrosine phosphatase activity
Biological process: presynapse assembly; synaptic membrane adhesion; trans-synaptic signaling by trans-synaptic complex; cell surface receptor protein tyrosine phosphatase signaling pathway; nervous system development; neuron differentiation; phosphate-containing compound metabolic process; positive regulation of dendritic spine morphogenesis; positive regulation of synapse assembly; presynaptic membrane assembly; signal transduction; trans-synaptic signaling
Cellular component: extracellular exosome; glutamatergic synapse; plasma membrane; membrane
Genetic constraint (gnomAD): Loss-of-function variants: 31 observed, 204.83 expected, observed/expected ratio (o/e) 0.15, 90% interval 0.11 to 0.2. The synonymous counts are far from expectation, so gnomAD's model fits this gene poorly and the ratio says little. Missense variants: 2,511 observed, 2,477.1 expected, observed/expected ratio (o/e) 1.01, 90% interval 0.98 to 1.05. Synonymous variants: 1,123 observed, 879.03 expected, observed/expected ratio (o/e) 1.28, 90% interval 1.22 to 1.34.
Homologues: Orthologues: macaque PTPRD (99% identical), pig PTPRD (99% identical), rabbit PTPRD (98% identical), mouse Ptprd (98% identical), rat Ptprd (98% identical), chimpanzee PTPRD (93% identical), guinea pig PTPRD (91% identical), tropical clawed frog ptprd (90% identical), zebrafish PTPRD (58% identical), zebrafish ptprdb (8% identical). Paralogues in human: PTPRS (72% identical), PTPRF (69% identical), PTPRK (23% identical), PTPRM (23% identical), PTPRZ1 (22% identical), PTPRT (22% identical), PTPRU (21% identical), PTPRG (20% identical), PTPRA (19% identical), PTPRE (17% identical), PTPRB (17% identical), PTPRC (16% identical), and 23 more.
Diseases named in the same sentence as PTPRD in open-access papers:
PTPRD is named in the same sentence as 175 diseases in open-access papers, as found by Europe PMC text mining. Sharing a sentence is not in itself a finding about the gene and the disease. The quoted sentences say what the papers report.
glioblastoma (23 papers, 2011 to 2025). The most malignant astrocytic tumor (WHO grade IV). "PTPRD encodes protein tyrosine phosphatase and is frequently inactivated in solid tumors such as glioblastoma." (PMID 36209207, 2022). "It is shown that the PTPRD gene is a tumor suppressor and mutation/downregulation in this gene was observed in multiple cancers including lung and glioblastoma multiforme (a fatal form of brain cancer)." (PMID 34503185, 2021). "PTPRD (down-regulated 11-fold), a tumor suppressor that is frequently mutated in glioblastoma, Ewing’s sarcoma, lung cancer, cutaneous squamous cell carcinoma, and laryngeal squamous cell carcinoma." (PMID 26847345, 2016). "Further exploration into the mechanistic function of PTPRD in glioblastoma demonstrated that the loss of PTPRD led to the accumulation of active phospho-STAT3 in a p16Ink4A−/− mouse model." (PMID 26474282, 2015). "Several studies have identified tumor-specific methylation of CpG islands within the 5′ end of the regulatory region of the genes encoding the receptor-type PTPs such as PTPRD in a wide range of adenocarcinomas, glioblastomas, and squamous cell carcinomas." (PMID 26079428, 2015). "Mutations within PTPRD have been associated with several cancers: glioblastoma multiforme and head and neck squamous cell carcinomas, and clear cell renal carcinoma." (PMID 25290448, 2014). "The PTPRD gene, specifically, is frequently inactivated by genetic (deletion, mutation, copy number loss) or epigenetic (hypermethylation) mechanisms in cancers, such as glioblastoma multiforme (GBM), colon cancer, breast cancer, neuroblastoma, lung cancer, and squamous cell carcinoma (SCC)." (PMID 30208623, 2018). "In addition, germ-line mutations of PTPRD are hypothesized to be involved in Ewing Sarcoma and glioblastoma." (PMID 25138050, 2014). "We have previously shown that PTPRD is dysregulated in patients with glioblastoma and in EC, whilst its expression is significantly downregulated in patients with obesity." (PMID 40871563, 2025). "PTPRD is one of the most frequently inactivated genes across human cancers, including glioblastoma multiforme (GBM)." (PMID 40564862, 2025). "This study investigates the expression of PTPRD in endometrial cancer (EC) and the placenta, as well as in glioblastoma (GBM)." (PMID 38339334, 2024). "As such, in this study, we investigated the expression of PTPRD in endometrial cancer (EC) and the placenta, as well as in glioblastoma (GBM)." (PMID 38339334, 2024). "PTPRD, a receptor protein tyrosine kinase, has been previously identified as a target of inactivating alteration in glioblastoma." (PMID 35943799, 2022). "In the TCGA rearrangement cohort of 59 diffuse gliomas, there were four samples harboring intragenic PTPRD rearrangements: one grade 2 oligodendroglioma and three grade 4 IDHwt glioblastomas." (PMID 35982066, 2022). "PTPRD expression is commonly downregulated by genetic or epigenetic alterations in various cancer types, including glioblastoma and head and neck cancer." (PMID 31805999, 2019). "Homozygous deletions and/or epigenetic silencing of PTPRD have also been identified in multiple human cancers, including glioblastoma, lung carcinoma and head and neck carcinoma, indicating that PTPRD is a tumor-suppressor gene." (PMID 29844865, 2018). "In glioblastoma PTPRD was shown to be deleted through array comparative genomic hybridization and copy number analysis." (PMID 26474282, 2015). "PTPRD is one of the most frequently inactivated genes across human cancers, including glioblastoma multiforme." (PMID 26079428, 2015). "Our observation is in agreement with a series studies revealing that PTPRD expression is frequently lost or reduced in a number of human cancer tissues and cell lines, including lung cancer and glioblastoma multiforme." (PMID 25412184, 2014). "Recently, two studies showed DNA hypermethylation of PTPRD in glioblastoma and breast cancer cell lines." (PMID 25412184, 2014).
glioblastoma (continued). "PTPRD DNA methylation was especially detected in IDHwt glioblastomas irrespective of the copy number status, and it was associated with reduced PTPRD expression." (PMID 35982066, 2022). "Further, PTPRD is a known tumor suppressor for lung cancer; glioblastoma." (PMID 28324520, 2015). "PTPRD is a known tumor suppressor for lung cancer and glioblastoma." (PMID 21386901, 2011). "Therefore, exogenous expression of PTPRD inhibits cell growth in human glioblastoma, suppresses colon cancer cell migration, and decreases cell viability by inducing apoptosis in melanoma cells, indicating that the loss of PTPRD promotes an aggressive cancer phenotype." (PMID 31805999, 2019). "Furthermore, we have expanded our observations on the expression of PTPRD in glioblastoma multiforme (GBM; a highly heterogeneous type of brain tumour, characterised by rapid cell division and extensive proliferation)." (PMID 38339334, 2024).
lung carcinoma (18 papers, 2011 to 2025). "PTPRD mutations have been found in lung cancer and other malignancies." (PMID 26629988, 2015). "Moreover, variant interpreters were more over single tools but not reflections of real influences, plasmid containing specific alteration was suggested to transfected into lung cancer cells to validate the predictions of specific mutations’ effects on PTPRD biological functions." (PMID 34615542, 2021). "Like PTPRD, PTPRT is inactivated by mutation in many cancers, including lung cancer, gastric cancer, and head and neck SCC, and it is most frequently mutated in colorectal cancer (CRC)." (PMID 30208623, 2018). "A recent study showed reduced PTPRD expression in the majority (>80%) of cell lines and surgical specimens of lung cancer, indicating that PTPRD is a candidate tumor suppressor." (PMID 25412184, 2014). "The PTPRD gene is located at chromosome 9p23–24.1, a locus frequently lost in neuroblastoma, gliomas, lung cancer and other malignancies." (PMID 25412184, 2014). "PTPRD has been suggested to function as a tumour suppressor in several tumours, including lung cancers and brain tumours." (PMID 23289484, 2013). "Two other top genes in African-Americans (CDH13 [MIM 601364] and PTPRD [MIM 601598]) are related to lung cancer and childhood asthma." (PMID 23829686, 2013). "PTPRD is previously reported candidate tumor suppressor gene in lung cancer." (PMID 28324520, 2015). "PTPRD was also shown to be involved in colon cancer cell migration via a β-catenin/TCF/CD44 signalling pathway, whereas in lung cancer PTPRD appears to act as a tumour suppressor gene." (PMID 40871563, 2025). "PTPRD has also been shown to be involved in colon cancer cell migration via a β-catenin/TCF/CD44 signalling pathway, whereas in lung cancer, PTPRD appears to act as a tumour suppressor gene." (PMID 38339334, 2024). "PTPRD homozygous or heterozygous deletion has also been reported in cutaneous squamous cell carcinoma, GBM, lung cancer, neuroblastoma, metastatic melanoma, squamous cell carcinoma of the vulva, hepatocellular carcinoma, and laryngeal squamous cell carcinoma." (PMID 26267899, 2015). "PTPRD and EPHA7 mutation are two new biomarkers for predicting the efficacy of immunotherapy independent of TMB or PD-L1 expression in lung cancer." (PMID 36845145, 2023).
melanoma (17 papers, 2013 to 2025). A malignant, usually aggressive tumor composed of atypical, neoplastic melanocytes. "PTPRD mutation was modestly associated with overall survival in melanoma and NSCLC cohorts, though this relationship was more significant than that between total mutational burden and overall survival." (PMID 35798829, 2022). "Further research found that CARD11 and PTPRD mutations were significantly associated with more tumor-infiltrated immune cells in melanoma samples." (PMID 36120536, 2022). "We also found that PTPRD was linked to OS in melanoma patients treated with ICIs and in bladder cancer patients, there was also a such tendency (p=0.062)." (PMID 34615542, 2021). "For melanoma patients, PTPRD mutation group had longer median OS than WT (over 80.00 vs 41.00 months, HR=0.55, p=0.0215)." (PMID 34615542, 2021). "Mutations in PTPRD stimulate cell migration and growth in melanoma cell lines, enhance cell proliferation, and abrogate the dephosphorylation of Signal transducer and activator of transcription 3 (STAT3) in human astrocytes." (PMID 33436679, 2021). "PTPRD mutations were most common in melanoma and NSCLC patients, followed distantly by colorectal cancer, cancers of unknown primary origin, esophagogastric cancer, bladder cancer, and HNSCC." (PMID 35798829, 2022). "Base on a public cohort, we analyzed the predictive efficiency of PTPRD mutation in other cancer types, including colorectal cancer, bladder cancer, head and neck cancer, esophagogastric cancer, melanoma, and unknown primary cancers." (PMID 34615542, 2021). "The mutational inactivation of PTPRD in glioblastoma was linked to melanoma malignancy." (PMID 34615542, 2021). "In general, PTPRD mutations may also predict OS for melanoma patients with ICIs but still need more validation." (PMID 34615542, 2021). "As TET1 and PTPRD mutations were the only significant predictors of outcomes in the melanoma discovery cohort, we next explored their prognostic utility in a valuation cohort consisting of melanoma patients from three independent immunogenomic studies all receiving ICIs (N = 212)." (PMID 35798829, 2022). "Additionally, we identified very frequent mutations (18 missense and 1 deleterious) in PTPRD, a tumor suppressor frequently mutated in many cancers, including melanoma and cutaneous SCC, in 13 samples, but these have never been reported as frequently mutated in BCC." (PMID 34900699, 2021). "Our study has also identified several additional candidate biomarkers in other tumor types, including PTPRD for melanoma and NSCLC patients." (PMID 35798829, 2022). "Specifically, PTPRD has been shown as tumor suppressor in glioma, liver, lung, head and neck, colorectal and melanoma." (PMID 26474282, 2015). "The PTPRD gene was positively correlated with C1GALT1 expression in kidney‐clear cell carcinoma and other cancers such as colon, head and neck, thyroid, prostate, breast, ovarian, liver cancers, and melanoma." (PMID 40548474, 2025). "Notably, the canine oral melanomas in our series also lacked SF3B1 and GNAQ mutations, and no mutations in POLE, PTPRD, or DMXL2 were found, suggesting that these canine cancers may not represent a faithful genetic model for the subset of human mucosal melanomas with mutations in these genes." (PMID 30664638, 2019).
breast carcinoma (13 papers, 2014 to 2025). "There are a few SV regions that harbouring breast cancer associated tumour suppressor genes, such as PTPRD in HCI008 model and CSMD3 in HCI012 model." (PMID 36153537, 2022). "PTPRD alterations occurred in 7% of all breast cancer cases, and the mutant PTPRD variant was associated with high frequencies of mutation in other genes." (PMID 29228728, 2017). "Whole exome sequencing data of 510 breast cancer specimens highlighted PTPRD as one of the most significantly mutated genes." (PMID 29228728, 2017). "Taken together, these data indicate that E2F2 loss results in increased metastasis in breast cancer, potentially functioning through a PTPRD dependent mechanism." (PMID 26474282, 2015). "Our data suggests an additional role for PTPRD in mediating breast cancer metastasis in conjunction with the loss of E2F2." (PMID 26474282, 2015). "Taken together these findings suggested that E2F2 loss regulated breast cancer metastasis in a subpopulation of human tumors, potentially through a PTPRD signaling axis." (PMID 26474282, 2015). "Interestingly, PTPRD was recently identified in the TCGA project as being significantly mutated in breast cancer." (PMID 26474282, 2015). "Previous studies have demonstrated that PTPRD exerts a suppressive effect in breast cancer and liver cancer." (PMID 36248841, 2022). "PTPRD is associated with negative regulation of stemness, epithelial-mesenchymal transition (EMT), and migration and invasion in breast cancer cells." (PMID 34359773, 2021). "In vitro, PTPRD silencing using siRNA enhanced the stem cell-like properties of breast cancer cells, including their mammosphere- and holoclone-forming abilities, and it promoted tumorigenicity in vivo." (PMID 29228728, 2017). "Our current data showed that PTPRD downregulation significantly induced breast cancer cell EMT by promoting, in parallel with increased vimentin and decreased E-cadherin expression, their migratory and invasive capacities." (PMID 29228728, 2017). "More and larger clones were formed by breast cancer cells transfected with PTPRD siRNA than by the cells transfected with NC siRNA (P < 0.01)." (PMID 29228728, 2017). "Despite the high prevalence of PTPRD inactivation in breast cancer and other tumors, the role of PTPRD in tumor progression is not yet fully understood." (PMID 29228728, 2017). "PTPRD knockdown also increased the CD44+/CD24− breast cancer stem cell (BCSC) population and the expression of the stem cell markers ALDH1 and OCT4." (PMID 29228728, 2017). "To test this possibility, we evaluated IL-6-mediated STAT3 phosphorylation in both control and PTPRD-silenced breast cancer cells." (PMID 29228728, 2017). "To define the molecular functions of PTPRD in breast cancer, we first performed transient small interference RNA (siRNA)-mediated PTPRD knockdown in MDA-MB-231 and MCF-7 cells." (PMID 29228728, 2017). "The PTPRD gene is frequently inactivated in various human cancers, including lung, colorectal, and breast cancers, glioblastoma, clear cell renal cell carcinoma, and melanoma." (PMID 29228728, 2017). "On the other hand, western blotting and immunohistochemistry analyses indicated decreased PTPRD and increased pSTAT3 expression in samples from PTPRD shRNA-transfected breast cancer cells, compared with NC shRNA controls." (PMID 29228728, 2017). "Both in vitro and in vivo tests revealed that PTPRD activity was required for migration and colonization by human breast cancer cells." (PMID 26474282, 2015). "Survival analysis showed that overexpression of PTPRD decreased time to distant metastasis in the basal subtype of human breast cancer." (PMID 26474282, 2015).